ALB (albumin)
Diseases named in the same sentence as ALB in open-access papers (continued):
Sharing a sentence is not in itself a finding about the gene and the disease.
mastitis (25 papers, 2016 to 2025). Inflammation of breast tissue during lactation or postpartum due to an obstructed duct or infection. "A decreased A/G ratio is observed when an impaired blood–milk barrier causes an increase in serum albumin levels in the milk, and globulin production is elevated in response to inflammation in cows with subclinical mastitis." (PMID 39210789, 2025). "In general, mastitis may result in an increase in the level of proteinous compounds associated with the inflammatory and immune response such as albumin and immunoglobulins and a decrease in the endogenous milk proteins such as caseins." (PMID 28919679, 2017). "Mastitis-induced changes in osmotic gradients facilitate the leakage of plasma proteins such as albumin and fibrinogen into milk, further altering milk protein composition and potentially compromising dairy processing quality." (PMID 40901059, 2025). "On the day of disease incidence, Holstein cows with subclinical mastitis had reduced basophil count, A/G ratio, and levels of total cholesterol, albumin, and BUN and elevated globulin levels." (PMID 39210789, 2025). "ALB, synthesized predominantly in the liver, typically decreases during inflammatory conditions like endometritis and mastitis." (PMID 39335224, 2024). "New mastitis biomarkers under development are the levels of chaperonins for pathogen recognition, prostaglandin D synthase, serotransferrin, bovine serum albumin, various caseins, cytochrome C oxidase, annexin V, haptoglobin and many more." (PMID 34361932, 2021). "In individuals with mastitis, the blood-milk barrier leaks, which are characterized by serum albumin translocation into milk and a reduced expression of TJs." (PMID 34297785, 2021). "Previous proteomic studies reported that serotransferrin and serum albumin were elevated in response to other bacterial infections resulting in mastitis." (PMID 33260718, 2020). "For example, concentration of serum albumin increases in milk during mastitis because of an alteration in the blood–milk barrier." (PMID 28966615, 2017). "Consistently, our results demonstrate that treatment of sodium propionate can restore the blood–milk barrier function through inhibiting the downregulation of TJ and the leakage of FITC albumin in LPS-induced mastitis in mice." (PMID 28966615, 2017). "Subclinical mastitis was significantly associated with milk yield, EC, basophil count, A/G ratio, and levels of total cholesterol, albumin, globulin, BUN, milk SCC, milk lactose, milk non-protein nitrogen, and milk solids-not-fat." (PMID 39210789, 2025). "Additionally, mastitis-affected cows had higher total protein and globulin levels and increased somatic cell counts (SCCs), while albumin concentrations were decreased." (PMID 38003812, 2023). "In addition, studies have confirmed that activation of ALB expression can reduce the inflammatory damage of mastitis and inhibit the release of inflammatory cytokines." (PMID 35757473, 2022). "However, in dairy cows with hoof disease, mastitis, and postpartum metritis, significant decreases in albumin and increases in alpha 1 and beta globulins were observed." (PMID 33996975, 2021). "Therefore, studies have reported a significant increase in whey proteins and albumin concentration during mastitis, but major changes are observed in casein proportion due to pronounced hydrolysis following plasmin activity." (PMID 33114454, 2020). "The high abundance protein and APP profiles of milk during an experimental S. uberis mastitis challenge were investigated, with a shift in abundance from caseins, β-lactoglobulin and α-lactalbumin to albumin, lactoferrin and IgG being observed following infection." (PMID 27412456, 2016). "The increased duration of low pH caused by the FBH diet may enhance liver-mediated inflammation, laminitis, mastitis, metritis ruminitis and oxidative stress in some individuals within the herd, and further evaluation of serum albumin A concentration is required." (PMID 32751524, 2020).
mastitis (continued). "The most important parameters in milk for diagnosing subclinical and clinical mastitis are the concentrations of LDH and total milk protein, as well as the concentrations of albumin and globulin in blood serum." (PMID 38003812, 2023). "The most important changes in the metabolic profiles of cows affected by mastitis are related to the energy status (NEFAs and BHB), the protein status (total protein, albumin, and globulin), and enzyme activity." (PMID 38003812, 2023). "On the other hand, higher concentrations of albumin, ALT, creatinine, triglycerides, and calcium were recorded in the blood serum of healthy cows in comparison to cows affected by mastitis." (PMID 38003812, 2023). "Proteins that stand out as logical candidates for further analyses include various APPs and vascular-derived proteins such as C3, C4, TF, ALB, TTR, FGA, and ITIH4 in mastitis whey of E. coli infected cows by 2-DE and label-free methods, respectively." (PMID 36335251, 2022). "In contrast, the blood levels of ALB, ALT and LDH were significantly lower in cows with subclinical mastitis than in healthy cows." (PMID 28240296, 2017). "Blood ALB, ALT and LDH levels in cows with subclinical mastitis were significantly increased after melatonin treatment compared with their untreated counterparts (p < 0.05)." (PMID 28240296, 2017). "Therefore, caseins were not profoundly affected, and only minimal changes in serum albumin concentration were observed, which is known to be secreted in cow’s milk with colibacillary mastitis." (PMID 33114454, 2020).
nephritis (25 papers, 2014 to 2025). Inflammation of renal tissue. "Kidney dysfunction is associated with the development of nephritis with a subsequent decrease in serum ALB and increases in BUN and CRE41." (PMID 33707585, 2021). "Although proximal tubular damage can be observed in this animal protocol, we cannot distinguish whether these damages were caused by an albumin-overload or BSA nephritis, which is a limitation of this study protocol." (PMID 31101909, 2019). "Moreover, the nephrotoxic nephritis model of renal injury also demonstrated protective effects of podocyte Shp2 deficiency as evidenced by lower urine albumin/creatinine and blood urea nitrogen in knockout mice than controls." (PMID 28352079, 2017). "Several of the N-terminome driven MOFA factors associated with kidney phenotypes with a more relaxed statistical criterion, among these factors 5 (nephritis), 7 (eGFR, urinary albumin/creatinine ratio), and 10 (proteinuria, nephritis, creatinine)." (PMID 41145914, 2025). "The clinical biomarker that performed best at assessing the severity of nephritis was urinary albumin concentration with excellent AUC values (AUC 0.81–0.98) in determining the grade of histological inflammation in IgAV-N." (PMID 33993342, 2021). "The rat anti‐Thy‐1 nephritis model was successfully established, according to increased urine albumin/creatinine ratio (UACR) in model group." (PMID 33987885, 2021). "In citrinin toxicity, inability to filtrate citrinin bound serum proteins and albumin leads to immune complex-induced nephritis." (PMID 29657389, 2018). "We showed that hAAT treatment resulted in significant decreases in proteinuria and urine albumin concentration, as well as nephritis." (PMID 27232337, 2016). "Celastrol-albumin nanoparticles crosses fenestrated endothelium and accumulates in mesangial cells, alleviating proteinuria, inflammation, glomerular hypercellularity, and excessive extracellular matrix deposition in rat anti-Thy1.1 nephritis models." (PMID 29026082, 2017). "In addition, kidney inflammation increases capillary permeability and escape of serum albumin into the interstitial space, leading to its expansion and increasing the distribution volume of albumin while shortening the half-life and decreasing total albumin mass." (PMID 39941432, 2025). "Urinary albumin to creatinine ratio (UACR) was measured to further validate the exacerbation and resolution of kidney inflammation during this course." (PMID 39493754, 2024). "Vehicle-treated mice exhibited progressive proteinuria, high urine albumin-to-creatinine ratio, elevated BUN levels, and evidence of severe nephritis based on pathology." (PMID 37441081, 2023). "Patients with class IVG had the most severe nephritis as follows: SBP, 144.2 ± 22.8 mmHg; DBP, 89.5 ± 14.2 mmHg; serum creatinine, 1.5 ± 1.1 mg/dL; estimated GFR, 68.4 ± 37.2 mL/min/1.73 m2; urinary protein, 4.7 ± 3.3 g/gCr; serum albumin, 2.8 ± 0.6 g/dL; and hemoglobin, 10 ± 2.2 g/dL." (PMID 25874130, 2015).
nosocomial infection (25 papers, 2012 to 2026). An infection acquired in a hospital or other healthcare setting. "In multivariable analysis, LBP, CRP, and albumin remained independently associated with nosocomial infection." (PMID 41574679, 2026). "This study showed that continuous infusion of 4% albumin reduced the risk of nosocomial infections in patients in the ICU." (PMID 38500153, 2024). "Several studies revealed that low serum albumin was considered a high-risk factor for deterioration and poor prognosis in patients with nosocomial infection." (PMID 35095715, 2021). "It was reported that serum albumin level on admission is associated with nosocomial infection or mortality during admission." (PMID 33374807, 2020). "Serum albumin at admission, mechanical ventilation and severity of disease showed significant association with nosocomial infection, and these risk factors have been demonstrated by other studies." (PMID 26443996, 2015). "In children with nosocomial infections, the lactate/albumin ratio measured at 24 hours after admission showed the highest predictive value for mortality, indicating its potential role in dynamic risk assessment." (PMID 40938884, 2025). "Serum albumin at admission, mechanical ventilation, severity of disease and PICU length of stay are important risk factors for nosocomial infections." (PMID 26443996, 2015). "Future research could investigate the impact of peri-operative and nosocomial infections on LOS in patients with low albumin at admission." (PMID 40275223, 2025). "Furthermore, early nutritional supports are needed, and if necessary, infusion of plasma or albumin to improve the body's resistance to prevent and reduce the chance of nosocomial infection." (PMID 35392885, 2022). "In addition, these data have been supported by our clinical study in collaboration with the Intensive Care Unit of Strasbourg showing that infusion with a low concentration of albumin improves the recovery of patients with nosocomial infections." (PMID 35216181, 2022). "Another study combined albumin and PCT to uncover a ratio, where albumin/PCT ratio could be an additional diagnostic predictor for nosocomial infection in patients with ICH." (PMID 34685473, 2021). "In the logistic regression model, PLR was a risk factor for the nosocomial infections in patients treated with VA-ECMO outcome (odds ratio [OR] 5.478; 95% confidence interval [95%CI] 2.117–14.176; P < 0.001) after adjustment for sex, age, hemoglobin, albumin, duration of VA-ECMO treatment." (PMID 40460330, 2025). "Higher NLR were associated with an increased risk of nosocomial infections in patients undergoing VA-ECMO (odds ratio [OR], 4.858; 95% confidence interval [95% CI], 1.864–12.663) (P = 0.001), after adjusting for sex, age, hemoglobin, albumin, and duration of VA-ECMO treatment." (PMID 40460330, 2025). "In the hospital setting, higher levels of serum albumin have also been found to be correlated with lower in-hospital mortality, lower length of stay (LOS), higher quality of life, and lower rates of nosocomial infection." (PMID 28558699, 2017). "Serum albumin at admission, mechanical ventilation, severity of disease and PICU length of stay were also found as significant predictors of nosocomial infection." (PMID 26443996, 2015). "Age, gender, serum albumin at admission, severity of disease, length of stay in PICU, nutrition delivery approach, amounts of delivered caloric intake and occurence of nosocomial infection were recorded." (PMID 26443996, 2015). "Nosocomial infections developed in 10 of 26 non-survivors compared with 9 of 45 survivors after 48 hours of albumin treatment (P = .19, χ2 test)." (PMID 31446184, 2020). "Compared with patients with non-nosocomial infection, patients with nosocomial infection had significantly lower level of serum albumin at admission, more severe conditions(Class 2), higher rate of mechanical ventilation and invasive diagnosis operation and longer PICU length of stay." (PMID 26443996, 2015).
nosocomial infection (continued). "Compared with noninfected patients, those with nosocomial infection had higher WBC, CRP, PCT, LBP, lactate, international normalized ratio (INR), and total bilirubin (TB), lower albumin and sodium, a higher neutrophil-to-lymphocyte ratio (NLR), and a lower lymphocyte-to-monocyte ratio (LMR)." (PMID 41574679, 2026).
subarachnoid hemorrhage (25 papers, 2011 to 2026). A serious neurological disorder characterized by intracranial hemorrhage into the subarachnoid space. "Neutralization of Mincle by specific antibody or albumin attenuated neuronal cell death and improved neurological functions in subarachnoid hemorrhage." (PMID 40792209, 2025). "Albumin can predict the subarachnoid hemorrhage outcome in combination with other inflammatory indices (as opposed to being used alone)." (PMID 36552160, 2022). "Albumin administration has been proven to improve neurobehavior in experimental subarachnoid hemorrhage." (PMID 33522912, 2021). "Multivariable analysis of serum albumin levels in patients with spontaneous subarachnoid hemorrhage." (PMID 34765635, 2021). "Previous studies demonstrated that human serum albumin treatment had neuroprotective effects on focal and global cerebral ischemia, subarachnoid hemorrhage, and ICH." (PMID 33708336, 2021). "An example design was considered for the case of albumin use for patients with subarachnoid hemorrhage." (PMID 28886745, 2017). "A phase III trial to determine the efficacy of albumin in subarachnoid hemorrhage is currently in progress." (PMID 24579051, 2014). "A multicenter pilot trial was conducted to evaluate the safety and tolerability of human albumin in patients with subarachnoid hemorrhage." (PMID 24579051, 2014). "Correlation of serum albumin levels in patients with spontaneous subarachnoid hemorrhage." (PMID 34765635, 2021). "Previous studies also discovered that albumin might be able to attenuate excessive innate immunity in subarachnoid hemorrhage." (PMID 33522912, 2021). "Subarachnoid hemorrhage also induced albumin leakage in the white matter at 4 hours." (PMID 31568658, 2019). "Therefore, oxidized albumin levels increase after subarachnoid hemorrhage, which may induce endothelial injury and contribute to delayed cerebral vasospasm and DCI." (PMID 39539653, 2024). "Moreover, two recent studies that used AG for risk stratification in subarachnoid hemorrhage patients did not explore the supplementary effect of albumin correction or develop a prognostic model using ACAG." (PMID 38962480, 2024). "This study aimed to compare albumin and IMA levels in blood and cerebrospinal fluid (CSF) from 30 patients with spontaneous subarachnoid hemorrhage (SAH) and 15 patients with normal pressure hydrocephalus (NPH) at a single center between 2021 and 2022." (PMID 42195204, 2026). "In the Albumin in Subarachnoid Hemorrhage (ALISAH) trial, albumin was safe in patients with SAH, and improved outcomes were reported with no major complications." (PMID 38967704, 2024). "A prospective, multicenter study, Albumin in Subarachnoid Haemorrhage (ALISAH), designed to demonstrate the tolerability and safety of four doses of albumin is currently in progress." (PMID 21906344, 2011). "The Albumin in Subarachnoid Hemorrhage Pilot Clinical Trial (ALISAH, ClinicalTrials.gov registration number NCT01747408) was a prospective, open-label, dose escalation study examining four dosages of albumin in increasing magnitude." (PMID 28886745, 2017).
brain injury (24 papers, 2008 to 2026). Acute and chronic (see also brain INJURIES, CHRONIC) injuries to the brain, including the cerebral hemispheres, CEREBELLUM, and brain STEM. "Studies have shown that younger age, MCS diagnosis at admission, higher serum albumin levels, and the presence of pupil reflex are associated with improved prognosis at 6 months after brain injury." (PMID 38952644, 2024). "Our findings showed that younger age, MCS diagnosis at entry, higher serum albumin level, and the presence of pupillary reflex were associated with improved outcomes at 6 months after brain injury." (PMID 36817098, 2022). "Albumin is considered safe for use as a resuscitation fluid in most critically ill patients; however, in patients with traumatic brain injury, its use is associated with increased mortality." (PMID 36143427, 2022). "Albumin has been found to be associated with clinical outcomes in patients with traumatic brain injury and ischemic stroke, but its predictive value of short-term clinical outcomes in patients with pDOC remains uncertain." (PMID 36817098, 2022). "In traumatic brain injury trials, iso-oncotic albumin was associated with higher mortality than saline." (PMID 33317590, 2020). "Our findings provide insights on how albumin extravasation that occurs upon BBB dysfunction in various brain injuries can predispose neural circuitry to the development of chronic inhibition deficits." (PMID 28794441, 2017). "A decrease in albumin may lead to increased blood viscosity, which can affect cerebral perfusion and increase the risk of ischemic brain injury." (PMID 40520906, 2025). "Besides, iso-oncotic albumin in hypotonic solution was associated with higher mortality rate in traumatic brain injury patients, and greater fluid volume and hypotonic solution may further raise intracranial pressure, leading to a higher mortality." (PMID 33317590, 2020). "However, exogenous albumin has been reported to be associated with increased mortality in patients with traumatic brain injury, which may be due to albumin-induced increases in intracranial pressure." (PMID 30395651, 2018). "In a study of patients with traumatic brain injuries, serum creatinine levels along with uric acid, bilirubin, and albumin showed significant changes during the acute phase, with sex-specific differences in antioxidant status." (PMID 40427466, 2025). "Recently, the neutrophil-albumin ratio has been suggested as a superior prognostic biomarker for traumatic brain injury." (PMID 39685555, 2024). "Another study identified serum albumin and prealbumin as predictors for unfavorable outcomes in traumatic brain injury, but in the subgroup of sABI patients, just serum albumin remained significant." (PMID 37662048, 2023). "Except for patients with traumatic brain injury, evidence suggests that albumin is well tolerated as a resuscitation fluid." (PMID 36143427, 2022). "In acute brain injury, albumin's role is controversial: it may aid recovery after cerebral hemorrhage, but can worsen outcomes in traumatic brain injury." (PMID 41827398, 2026). "In trauma patients without burns, albumin resuscitation has been associated with a significantly higher mortality in patients with severe traumatic brain injury." (PMID 39600029, 2023). "However, for traumatic brain injury patients, L-HES and saline, both hypertonic solutions, were associated with better survival than hypotonic solution, including iso-oncotic albumin and balanced crystalloid." (PMID 33317590, 2020). "However, many patients (including some with traumatic brain injury) continue to be prescribed albumin." (PMID 28103931, 2017). "Further clinical studies must show in which clinical indications beyond hepatology this property can be particularly useful as also in what populations albumin could be harmful such as after traumatic brain injury." (PMID 26136776, 2015).